MB (myoglobin)
Diseases named in the same sentence as MB in open-access papers (continued):
Sharing a sentence is not in itself a finding about the gene and the disease.
coronary heart disease (8 papers, 2019 to 2026). "Moreover, with repeated-measure ANOVA, we found a significant increase in the myoglobin level in women with a coexisting ischemic heart disease and those whose LVEF significantly decreased (r ≤ −0.6) before/during/after TT (p = 0.01, p < 0.000 respectively)." (PMID 35884413, 2022).
Crush Syndrome (8 papers, 2015 to 2025). Severe systemic manifestation of trauma and ischemia involving soft tissues, principally skeletal muscle, due to prolonged severe crushing. "The main causes of renal damage in crush syndrome are renal hypoperfusion due to hypovolemia and nephrotoxic substances such as myoglobin and ROS21." (PMID 36114355, 2022). "Furthermore, extensive muscle destruction, electric power accidents and post-ischemic syndrome are often associated with a marked release of myoglobin (crush syndrome) which can result in an increase in blood viscosity, as shown in animal experiments." (PMID 25886728, 2015). "Pathologically, it contributes to crush syndrome-induced kidney injury via myoglobin-triggered M1 macrophage polarization through the RIG-I/Caspase-1/GSDMD axis, demonstrating its multifaceted roles in immunity and disease." (PMID 40491921, 2025). "Single immunochemistry staining was applied in diagnosing specific trauma due to its sensitivity in identifying the target protein, such as the IHC staining of tubular myoglobin aiding in the verification of crush syndrome in judicial autopsy." (PMID 38338938, 2024). "The findings of our study suggest that zinc chelators could contribute to the resolution of myoglobin-induced acute renal injury after crush syndrome by suppressing neutrophil infiltration in ischemia–reperfusion injured muscle." (PMID 36114355, 2022).
lymphopenia (8 papers, 2020 to 2023). Reduction in the number of lymphocytes. "Disease severity was associated with changes in innate monocytes and neutrophils, lymphopenia, disrupted cytokine production (increased IL-8 and IP-10/CXCL10 but reduced IFNλ2/3 and IFNγ), and increased endothelial injury (myoglobin, VCAM-1)." (PMID 37598150, 2023). "Compared with non-diabetic group, diabetic cases more frequently had lymphopenia and hyperglycemia, with higher levels of urea nitrogen, myoglobin, D-dimer and ferritin." (PMID 33776910, 2021).
rhabdomyosarcoma (8 papers, 1989 to 2025). A rare aggressive malignant mesenchymal neoplasm arising from skeletal muscle. "The neoplastic cells of rhabdomyosarcoma were positive for vimentin, desmin, myoglobin and muscle-specific actin." (PMID 36641746, 2023). "Pleomorphic rhabdomyosarcoma shows at least focally an expression of skeletal muscle-specific markers, i.e., myoglobin, MyoD1, or myogenin, and lacks positivity for melanocytic markers." (PMID 31309284, 2020). "In this study we wished to evaluate the role of a commercial antibody to myoglobin as a marker of rhabdomyosarcomas." (PMID 2757915, 1989). "The purpose of this investigation was to assess the sensitivity and specificity of myoglobin antiserum as a marker of rhabdomyosarcomas." (PMID 2757915, 1989). "Notably, the components of rhabdomyosarcoma exhibited a strong positive reaction for desmin and a moderate positive response for myoglobin, the undifferentiated spindle cell component demonstrated a positive immunoreactivity solely for vimentin." (PMID 40832615, 2025). "Rhabdomyosarcoma typically shows positive staining for myogenin, desmin, sarcomeric actin, and myoglobin, while it is usually negative for NKX2.2, CD99, CD45, cytokeratin (CK), S100, and neuron-specific enolase (NSE)." (PMID 40094002, 2025). "Negative myoglobin, cytokeratin, and S‐100 help to rule out rhabdomyosarcoma, sarcomatoid carcinoma, and melanoma, respectively." (PMID 35228875, 2022). "Staining for myoglobin, a marker for rhabdomyosarcoma, was equivocal, and desmin was negative." (PMID 41245941, 2025). "Lack of staining with desmin and myoglobin excludes the possibility of rhabdomyosarcoma." (PMID 19700883, 2009).
Stroke (8 papers, 2021 to 2025). Sudden impairment of blood flow to a part of the brain due to occlusion or rupture of an artery to the brain. "The H-FABP ≥ 0.2 ng/mL group showed higher SBP, prior stroke rate, and PA and also higher values in most of the cardio-specific biomarkers including CK-MB, NT-proBNP, TnI, myoglobin, cystatin-C and sST2 (p < 0.05)." (PMID 41010838, 2025). "Here, we report a platform for biosensing based on chelated Eu3+ against a range of proteins including biomarkers of cardiac injury (human myoglobin), stroke (glial fibrillary acidic protein (GFAP)), inflammation (C-reactive protein (CRP)) and colorectal cancer (carcinoembryonic antigen (CEA))." (PMID 33513673, 2021). "The AUCs for lipocalin-2, sP-selectin, glial cell-derived neurotrophic factor (GDNF), sVCAM-1, sRAGE, MMP-7, D-dimer, MMP-1, Apolipoprotein CIII, myoglobin and BNDF were ≥0.75 in predicting stroke amongst children with TBM." (PMID 33930055, 2021). "In addition, we observed trends (0.05<p-value≤0.09) in increased levels of GDNF, interleukin (IL)-7, MMP-9, lipocalin-2, IL-4, sP-selectin, and myoglobin, and lower levels of CC5a, in children with TBM-related stroke compared to TBM without stroke." (PMID 33930055, 2021).
hypothyroidism (7 papers, 2019 to 2025). Abnormally low levels of thyroid hormone. "Rhabdomyolysis, indicated by elevated CK and myoglobin, is a rare but recognized muscular manifestation of severe hypothyroidism, arising from metabolic disturbances that impair muscle membrane stability and mitochondrial function." (PMID 41267710, 2025). "However, rhabdomyolysis, defined as a process of acute lysis of striated muscle fibers with massive release of intracellular constituents such as CPK, myoglobin, potassium, and various muscle enzymes into the systemic circulation, remains a rare but potentially fatal complication of hypothyroidism." (PMID 40709115, 2025). "On investigations, he was found to have severe hypothyroidism, AKI along with raised creatinine kinase (CK) and myoglobin indicating severe muscle damage." (PMID 33880311, 2021). "These patients have elevated serum CK and myoglobin levels, though no direct correlation has been established between the severity of hypothyroidism and CK levels." (PMID 39429302, 2024).
infarction (7 papers, 2014 to 2024). A localised pathological necrosis of tissue resulting from obstruction of the blood supply usually by a thrombus, an embolus, or vascular torsion. "From the blood collection, it is possible to identify the biochemical markers of myocardial damage, such as troponin, CKMB, and myoglobin, which are essential for confirming a diagnosis of infarction." (PMID 37372853, 2023). "Myoglobin is a sensitivemarker for muscle injury, and its elevated level has specificity for acutemyocardial infarction." (PMID 29898033, 2018). "Furthermore, patients withcerebral infarction had significantly higher levels of blood sugar, lactatedehydrogenase, myoglobin, creatine kinase-MB, prothrombin time, internationalnormalized ratio (INR), fibrinogen degradation products (FDP) and D-dimer thancontrol patients (all p < 0.05)." (PMID 39077534, 2023).
injury (7 papers, 2014 to 2025). Damage inflicted on the body as the direct or indirect result of an external force, with or without disruption of structural continuity. "CK-MB is one of the isoenzymes of CK, which is associated with mitochondria and cytosol in muscle cells, and about 20% of CK in the myocardium is in the form of myoglobin, which provides sensitivity and specificity for the diagnosis of acute myocardial injury." (PMID 40284832, 2025).
malaria (7 papers, 2011 to 2024). Malaria is a serious and sometimes fatal disease caused by a parasite that commonly infects a certain type of mosquito which feeds on humans. "Microsporidia MB is a symbiont with a strong malaria transmission-blocking phenotype in Anopheles arabiensis." (PMID 38063396, 2024). "Heme-containing myoglobin concentrations are also increased in severe malaria, although to a much lesser extent than CFH." (PMID 28449641, 2017). "Circulation levels of cardiac proteins, such as troponin T (TnT), myoglobin and creatine kinase (CK), which are biomarkers of myocardial injury, increases with the severity of malaria, indicating myocardial impairment in complicated falciparum malaria." (PMID 27806725, 2016). "All cardiac proteins except for TnT were about twice as high in malaria patients compared to controls albeit at borderline statistical significance for NT proBNP and myoglobin." (PMID 21658247, 2011). "Levels of cardiac proteins were inconsistent in patients with uncomplicated and complicated malaria: While NT proBNP, myoglobin and H-FABP were highest in patients with complicated malaria the level of CK-MB in complicated malaria was comparable with the level in healthy controls." (PMID 21658247, 2011). "Myoglobin as an alternative source of heme-mediated oxidative damage was not assessed, but other studies have shown a 100-fold less increase in plasma myoglobin compared to CFH in patients with severe malaria." (PMID 28449641, 2017).
pneumonia (7 papers, 2017 to 2024). An acute, acute and chronic, or chronic inflammation focally or diffusely affecting the lung parenchyma, caused by an infection in one or both of the lungs (by bacteria, viruses, fungi, or mycoplasma.). "Univariate logistic regression analysis showed that severe group, WBC count, lymphocyte count, neutrophil count, LDH, CRP, SAA, HS-TnT, albumin, CKMB_M, myoglobin, and sodium were significantly associated with remission of pneumonia (all p < 0.05)." (PMID 37965268, 2023). "Older age (≥50 years), high levels of ALT and AST (both ≥ 40 U/L), critical and severe pneumonia, and high levels of myoglobin (≥100 μg/L) significantly increased the chance of longer LOS (all p < 0.05)." (PMID 34158873, 2021).
acute tubular necrosis (6 papers, 2012 to 2026). "Such elevation carries a significant risk for myoglobin-induced acute tubular necrosis (ATN) and warrants close renal monitoring." (PMID 41458824, 2025). "Renal biopsy studies have shown acute tubular necrosis being the most common finding followed by myoglobin casts and interstitial nephritis." (PMID 22953145, 2012). "Filtered myoglobin precipitates in the acidic and concentrated urine of the distal tubule, forming obstructive casts with Tamm-Horsfall protein, which is a central event in the development of acute tubular necrosis." (PMID 41479675, 2025).
kidney injury (6 papers, 2020 to 2025). Trauma to the kidney. "Haemoglobin and myoglobin can cause acute kidney injury by direct toxic effects on the tubular cells, renal vasoconstriction and tubular obstruction by cast formation." (PMID 36307881, 2022). "In contrast, myoglobin, a marker of skeletal muscle damage, showed elevated levels in the kidney injury group (r = -0.80, P < 0.01) and demonstrated a stronger association with early kidney injury than creatine kinase (r = -0.38, P < 0.05)." (PMID 39840004, 2024). "Regarding the markers for skeletal muscle damage, both myoglobin and CK levels were higher in the kidney injury group (P < 0.05 and P < 0.01, respectively)." (PMID 39840004, 2024). "Recent studies have reported that ERS and ferroptosis are involved in AKI induced by heat stress combined with myoglobin, and ERS inhibitors can effectively inhibit ferroptosis and alleviate heat stress and myoglobin-mediated kidney injury." (PMID 37408574, 2023).
renal dysfunction (6 papers, 2018 to 2025). "Our previous research revealed that serum myoglobin was obviously increased during the very early stages of renal injury, and the results of the present study revealed associated renal dysfunction." (PMID 29466390, 2018). "Renal dysfunction may be another important factor causing the dynamic increase in myoglobin level." (PMID 38264034, 2023). "Myoglobin is filtered by the glomeruli when large amounts are excreted, exceeding the binding capacity of plasma protein, and can eventually lead to tubule obstruction and renal dysfunction." (PMID 39964593, 2025). "Serum CK and myoglobin levels, mostly reflecting the initial muscle damage and usually normalizing within a few days once the injury ceases, have been shown to predict subsequent renal dysfunction." (PMID 39347295, 2024). "In addition, the details for equipment and techniques used for myoglobin removal and outcome measures like the length of stay and long-term renal dysfunction are also inconsistently reported." (PMID 37398832, 2023).
rhabdomyoma (6 papers, 2008 to 2025). A benign mesenchymal tumor arising from skeletal or cardiac muscle. "Immunoperoxidase staining can also help identify rhabdomyoma histology, with neoplastic muscle tissue staining positively for myoglobin and myogenin, and negatively for S100." (PMID 38963610, 2024). "Both rhabdomyomas and their malignant counterparts stain positively for myoglobin and demonstrate a cytoplasmic staining pattern." (PMID 38963610, 2024). "Adult rhabdomyoma staining will characteristically confirm skeletal muscle differentiation, with tumours positive for myoglobin, desmin and muscle-specific actin." (PMID 29744825, 2019). "Immunohistochemical studies show the striated muscle characteristics of rhabdomyoma cells, which express myoglobin, desmin, and actin." (PMID 22973317, 2012). "Interestingly, the resection specimen of this mass revealed adult rhabdomyoma that was confirmed by immunostains of myoglobin and myogen (interpretation error of benign tumor)." (PMID 18373853, 2008).
type 2 diabetes (6 papers, 2012 to 2022). "In our cross-sectional analysis of individuals with type 2 diabetes from three different cohorts, a multiplex proteomics assay identified four circulating proteins associated with DKD: KIM-1, GDF-15, myoglobin, and MMP-10." (PMID 31805809, 2020). "Salivary myoglobin levels have been used to confirm individuals with Type 2 diabetes and various autoimmune diseases." (PMID 23369566, 2012).
viral infection (6 papers, 2022 to 2026). "This phenomenon is consistent with viral diseases and macrophage damage caused by myoglobin, which is likely attributed to caspase-1 and RIG-I having structurally identical CARD regions." (PMID 40175216, 2025). "In the pancreas disease (PD), a viral disease of salmon, we see endothelial scavenger cells filled with small granules, presumably consisting of myoglobin from severe muscle necrosis." (PMID 40670973, 2025). "The observed cyclic myoglobin spikes highlight the dynamic nature of muscle injury following viral infections." (PMID 39347295, 2024). "In non-viral infection studies, our recently research have shown that RIG-I acts as a sensor for myoglobin to activate the RIG-I/NF-κB/Caspase3 signaling pathway, which promotes the secretion of inflammatory factors and mediates apoptosis in renal cells of CS-AKI rat." (PMID 35228524, 2022).
compartment syndrome (5 papers, 2017 to 2025). Elevated pressure in a confined space enclosed by fascia or eschar, which may lead to vascular compromise and subsequent ischemic injury to the tissue within the space. "For myoglobin, median levels of 1248 μg/L were found in patients with acute compartment syndrome associated with gynecological surgery, whereas median levels in patients without compartment syndrome were much lower (45 μg/L)." (PMID 30611244, 2019).
Hyponatremia (5 papers, 2013 to 2023). An abnormally decreased sodium concentration in the blood. "First, lower osmolality of the extracellular fluid in acute hyponatremia causes cell swelling, and lowered transmembrane potential hours after the extrusion of intracellular potassium causes the release of CPK and myoglobin." (PMID 27721999, 2016). "A 64-year-old Caucasian woman presented to our facility with worsening fatigue, slurred speech, nausea and vomiting, and high serum levels of creatine kinase and myoglobin together with hyponatremia." (PMID 24083446, 2013). "Peripheral blood tests revealed elevated creatine kinase (19,013 IU/L) and myoglobin (5099 U/L) levels and severe hyponatremia (111 mEq/L) with no azotemia." (PMID 34596163, 2021). "If the hyponatremia state is not corrected, the stressed cells release creatine kinase and myoglobin with cell injury." (PMID 28160775, 2017).
interstitial nephritis (5 papers, 2012 to 2025). Inflammation of the renal tubules and supporting tissues of the kidney. "Myoglobin can accumulate in renal tubules, causing obstruction and injury, known as myoglobinuric AKI; a significant factor for tubulointerstitial nephritis in heat stress nephropathy." (PMID 41141547, 2025). "A combination of myoglobin cast obstruction in the distal tubule and tubulointerstitial nephritis has been observed." (PMID 39720376, 2024).
leukocytosis (5 papers, 2020 to 2024). "In the literature, it has been reported to cause abnormalities in many cellular and biochemical parameters such as leukocytosis, leukopenia, neutrophilia, hypoalbuminemia, ferritin, troponin, and myoglobin." (PMID 37965400, 2023). "Laboratory tests revealed leukocytosis and elevated serum liver enzymes, myoglobin and lipase." (PMID 32670645, 2020).
polymyositis (5 papers, 2020 to 2023). A rare idiopathic inflammatory myopathy characterized by symmetric proximal muscle weakness and elevated muscle enzymes. "Moreover, in some neuromuscular diseases such as polymyositis/dermatomyositis and myasthenia gravis increased levels of circulating Hpx have been associated with myoglobin release." (PMID 33142923, 2020). "The clinical presentation in most cases resembles polymyositis, with elevated markers of muscle damage, such as creatine kinase and myoglobin." (PMID 36981837, 2023). "Another example is polymyositis, where anti-myoglobin aAbs correlate well with clinical activity, but do not participate in the induction of tissue destruction." (PMID 33776892, 2021). "DM is divided into two types based on whether it involves the derma and myoglobin or not: DM and polymyositis (PM)." (PMID 33407883, 2021).
Thrombocytopenia (5 papers, 2020 to 2022). A reduction in the number of circulating thrombocytes. "Laboratory investigations showed severe thrombocytopenia, leukopenia, impaired renal function, and elevated cardiac enzyme and myoglobin levels." (PMID 34823480, 2021).
cardiac arrhythmias (4 papers, 2021 to 2025). Any disturbances of the normal rhythmic beating of the heart or MYOCARDIAL CONTRACTION. "Moreover, it has been discovered that elevated levels of myoglobin may be due to other comorbidities, such as chronic obstructive pulmonary disease, cardiovascular disease, and so on." (PMID 38355552, 2024).
coagulopathy (4 papers, 2010 to 2025). "Myoglobin is an independent risk factor for coagulopathy (OR = 1.90, 95%CI: 1.45–2.49), SIRS (OR = 1.41, 95%CI: 1.10–1.79), and AKI (OR = 4.17, 95%CI: 2.19–7.95)." (PMID 40055771, 2025). "Notably, Myoglobin is an independent risk factor for early coagulopathy, SIRS and AKI in patients with multiple injuries." (PMID 40055771, 2025). "Among them, Myoglobin (OR = 1.82, 95%CI: 1.41–2.35) was a risk factor for coagulopathy." (PMID 40055771, 2025). "In case of a coral snake envenoming, serum creatine kinase activity may rise, and myoglobin may be detected in the urine, but coagulopathy is not a feature." (PMID 33995385, 2021). "We observed significant differences in the levels of Myoglobin, Creatine kinase-MB, Fibrinogen, RBC, Total Protein, Albumin between patients with coagulopathy and non-patients, and ISS and death outcomes were also different." (PMID 40055771, 2025).
hyperphosphatemia (4 papers, 2020 to 2023). Abnormally high level of phosphate in the blood. "Hereby, the correlation with lactate was stronger than with LDH, ASAT, ALAT, myoglobin or creatinine suggesting tissue ischaemia to contribute stronger to hyperphosphataemia than direct cellular breakdown in our cohort." (PMID 34573890, 2021).